CD55 (CD55 molecule (Cromer blood group))
Diseases named in the same sentence as CD55 in open-access papers (continued):
Sharing a sentence is not in itself a finding about the gene and the disease.
tumor (continued). "It affects tumor aggressiveness by binding its cellular ligand CD55 and exhibits adhesive properties." (PMID 25624904, 2015). "CD97 and CD55 have been found in the tumor microenvironment and contribute to metastasis and invasion, leading to a poor prognosis." (PMID 25624904, 2015). "In this study, we have found that the complement system is unexpectedly activated in latently KSHV-infected endothelial cells and in KS tumor cells wherein KSHV downregulates the expression of CD55 and CD59 complement regulatory proteins." (PMID 25254972, 2014). "CD97 with adhesive properties belongs to the epidermal growth factor-transmembrane 7 family and is known to play an important role in tumor differentiation, invasiveness, and metastasis by binding to its cellular ligand CD55." (PMID 21637820, 2011). "Membrane complement resistance factors CD55 and CD59 have been reported as markers of tumour aggression, and have been associated with reduced survival in CRC patients." (PMID 21339979, 2010). "791T/36 was subsequently shown to recognise CD55, a complement regulatory protein overexpressed by tumours to protect them from complement attack." (PMID 15798769, 2005). "Tumour cells showed a 4–100-fold increase in CD55 cell surface expression when compared to normal cells." (PMID 11139317, 2001). "Tumour cell lines deposit CD55 into their extracellular matrix (ECM) in direct proportion to their cell surface expression." (PMID 11139317, 2001). "Inhibiting LGALS3 could potentially synergize with chemotherapy to break through stromal barriers, while blocking CD55 could restore complement-mediated tumor lysis." (PMID 40723289, 2025). "We are very concerned about the effect of CD55 on tumor cells." (PMID 40596619, 2025). "Additionally, the complement regulatory protein CD55 was also overexpressed, likely providing protective mechanisms for tumor cells against immune-mediated destruction." (PMID 40723289, 2025). "Known as a complement decay accelerator, CD55 is involved in tumor dedifferentiation, proliferation, invasion, and migration and its upregulation may be associated with tumor progression." (PMID 40535127, 2025). "Furthermore, bsAbs binding tumor antigens and membrane-bound complement inhibitors (e.g., Crry or CD55) have been shown to induce killing of tumor cells by blocking these inhibitors specifically on tumor cells." (PMID 38817607, 2024). "Furthermore, this anti-CD55 antibody attenuated LoVo tumor growth in mice and decreased in vitro metastatic invasion of DLD-1 cells." (PMID 38612911, 2024). "Our results suggest that an asymmetric bispecific antibody that simultaneously targets CD55 and a tumor-specific antigen could improve tumor cell-killing activity beyond that demonstrated by conventional symmetric monospecific or bispecific antibodies." (PMID 37880350, 2023). "CD55 is expressed on nearly all cells of the body and overexpressed on tumor cells." (PMID 36717781, 2023). "Notably, this innovative antibody excelled in promoting CDC-mediated tumor cell elimination, surpassing the effectiveness of both rituximab and a combined rituximab/anti-CD55 antibody (4-1H)." (PMID 37880350, 2023). "We found that, while this reduced dose of T+P could only moderately inhibit control KPL-4 tumor growth, knockdown of CD55 and CD59 in the same tumors resulted in profound tumor growth suppression." (PMID 35167491, 2022). "We assessed tumor cell characteristics associated with immune suppression (PD-L1, CD47, and HVEM) or known tumor features associated with response/resistance to daratumumab treatment (expression levels of CD38 and the complement inhibitory proteins CD55 and CD59)." (PMID 34070044, 2021). "The pretreatment expression of CD38 was correlated with a better outcome to daratumumab, while lack of response and tumor progression was associated with expression of both CD55 and CD59." (PMID 34299097, 2021). "The authors found that inhibition of CD55 resulted in a 76% decrease in overall tumor burden." (PMID 34572075, 2021).
tumor (continued). "Moreover, compared with ductal-normal and ductal-tumor cells, CD55_ADGRE5, CD99_PILRA, ANXA1_FPR3 interactions were drastically upregulated in the malignant cells." (PMID 35087839, 2021). "Moreover, a great deal of data showed that mCRP expression, contains CD46, CD55, and CD59, are linked to worse clinical outcomes, and in some cases highly specific for tumor cells, many approaches to block mCRP expression on tumor cells have been studied." (PMID 33614473, 2020). "The role of complement activation and membrane inhibitors expressed by tumor cells, most notably CD55 and CD59, has also been quite extensively studied, but how much these affect the resistance of tumors in vivo to IgG1 therapeutic mAbs still remains incompletely understood." (PMID 33126570, 2020). "In addition, patients with an increased CD55 expression in their tumor tissue had a worse 7-year survival rate, with tumors with high levels of CD55 more aggressive than tumors with low CD55-levels." (PMID 33362763, 2020). "Moreover, the expression of E1A, TRAIL and MnSOD was increased in tumour mass with the treatment of Dox plus CD55‐TMn compared to CD55‐TMn alone in vivo." (PMID 33251723, 2020). "Therefore, Dox can enhance apoptosis inducement effect of CD55‐TMn, and the combination treatment can more effectively kill the tumour cells via inducing cell apoptosis compared with each treatment alone." (PMID 33251723, 2020). "Therefore, CD55-Smad4 suppressed metastasis and tumor cell stemness in CRC by regulating the Wnt/β-catenin signaling pathway." (PMID 33322272, 2020). "Compared to other treat‐group alone, Dox treatment increased cell apoptosis in tumour tissue treated with CD55‐TMn via TUNEL analysis, and the combination therapy can induce more severe cytopathic effects of tumour tissue that was examined by haematoxylin and eosin (HE) staining." (PMID 33251723, 2020). "Notably, CD55-Smad4 effectively suppresses cell metastasis and tumor cell stemness in CRC by regulating the Wnt/β-catenin signaling pathway." (PMID 33322272, 2020). "Because of the great deal of data showing that CD46, CD55, and CD59 expression are linked to worse clinical outcomes, and are in some cases highly specific for tumor cells, many approaches to block mCRP expression on tumor cells have been studied." (PMID 31164885, 2019). "Alternatively, the expression of CD55 could prevent complement mediated killing of premalignant cells, resulting in decreased control of tumor growth." (PMID 31164885, 2019). "Elements of the ComC may protect tumor cells from NK attack by membrane-bound or soluble regulators (e.g., CD55, CD59, and factor H) and by suppression of anti-tumor T cell immunity." (PMID 31231394, 2019). "Therefore, we investigated the expression of ER subtypes in human cSCC A431 cells and the effects of ER subtype activation by ER agonists on the expression of tumor markers CD55 and Cyclin D1." (PMID 31611744, 2019). "Apart from CD59, CD46, and CD55 could also enable tumor cells to evade CDC and function as complement regulators." (PMID 31685825, 2019). "Interestingly, in some MM tumors there are coexisting subpopulations of tumor cells with markedly different levels of CD55 and CD59 expression." (PMID 30294326, 2018). "Additionally, combined treatment of H368 tumor cells with 177Lu-anti-CD55 and cisplatin led to a 47.9% reduction in cell viability, which was also indicative of a synergistic effect." (PMID 29895866, 2018). "The 177Lu-anti-CD55 antibody was predominantly retained in tumor tissues at all time points." (PMID 29895866, 2018). "Anti-CD38 treatment may also generate resistance and induce tumor immune escape, through the up-regulation of two complement inhibitor proteins, CD55 and CD59 on MM cells." (PMID 30546360, 2018).
tumor (continued). "To further validate the effect of CD55 silencing on cisplatin resistance, we injected CD55-silenced and control CSCs into a total of 45 mice at a concentration of 2 million cells/mouse and waited until each mouse developed a 1-cm tumor." (PMID 28838952, 2017). "Moreover, CD55-silenced tumors demonstrated higher degrees of cell death and tumor regression, inflammatory cell infiltrate, and fibrosis compared with nontargeted controls treated with cisplatin." (PMID 28838952, 2017). "Thanks to accessibility of the CD55 cell surface protein, this marker will provide a ready target for the monoclonal antibody in order to destroy a small cell population within tumors responsible for tumor recurrence." (PMID 27043658, 2016). "We sought to determine whether the CD55+ cell subpopulation might promote the aggressive behavior of the heterogeneous tumor cell lines." (PMID 27043658, 2016). "In addition, CD97 and CD55 expression levels were found to significantly correlate with tumor aggressiveness (P<0.01)." (PMID 25624904, 2015). "Quantitative expression of CD55 in the tumour environment was therefore studied." (PMID 11139317, 2001). "Although it remains unclear why CD55 is upregulated in the tumour environment its high level of expression on tumour cells and associated endothelium may explain why it is a good target for both imaging and immunotherapy." (PMID 11139317, 2001). "Although there is a view that the destruction of CD55 may have an anti-cancer effect on a variety of cancers, this view is based on the ability to detect a large amount of CD55 expression in tumor tissues, but whether CD55 can be used as a key target in tumor treatment remains to be studied." (PMID 40596619, 2025). "However, given the potential tumor-promoting effects of complement activation, CD55+ LAND-Vs could also be of therapeutic value in modulating the tumor microenvironment." (PMID 40383810, 2025). "In summary, this study uncovered a new role of complement in B-cell-dependent anti-tumor immunity and indicated that CD55 induced chemo-resistance by impeding the induction of ICOSL+ B cells and could thus be a potential therapeutic target to enhance the efficacy of immunogenic chemotherapy." (PMID 35795050, 2022). "Notably, high expression of CD55 can also promote the dissemination of tumor cells in circulation." (PMID 36741376, 2022). "Collectively, this study uncovered a new role of complement in B-cell-dependent anti-tumor immunity and indicated that CD55 induced chemo-resistance by impeding the induction of ICOSL+ B cells and thus could be a potential therapeutic target to enhance the efficacy of immunogenic chemotherapy." (PMID 33717201, 2021). "Therefore, evidence for a correlation between CD55 and immune cells is insufficient, and the mechanism by which CD55 acts in tumor immunity remains unclear." (PMID 33614473, 2020). "Our hypothesis is that the great amount of CD55 released by the small CD55+ cell subpopulation has an autocrine effect on CD55+ cells and a paracrine effect on CD55− cells by leading to the activation of downstream pathways involved in tumor malignant transformation." (PMID 27043658, 2016). "Sponges miR-216b and miR-150 to upregulate CD55 and CD59 expression and suppress complement system activation to promote tumor immune evasion." (PMID 41409273, 2025). "Further analysis revealed that Pygo2+ CD8+ T cells primarily engage with tumor cells and macrophages through immune checkpoint receptor-ligand pairs, such as CD74, CD55, and SPP1." (PMID 40771810, 2025). "Although the MAC can directly lyse tumor cells by disrupting membrane integrity, CRC cells evade complement-mediated cytotoxicity by upregulating CRPs such as CD55, CD46, and CD59 via STAT3/STAT6/p38 MAPK signaling." (PMID 41031883, 2025). "These myCAFs exhibited strong interactions with cytotoxic T/NK cells through the ICAM1, CD55, CXCL13, and CXCL16 signaling pathways, suggesting a potential contribution to tumor regression." (PMID 40107247, 2025).
tumor (continued). "CD55 and CFH were explored as predefined candidate IHC biomarkers and using archival tumor specimens from the time of initial diagnosis." (PMID 39747856, 2025). "Neutralizing antibody treatment against CD55 (decay accelerating factor) and CD59 results in complement and CD8 + T cell activation and inhibits tumor growth." (PMID 39747856, 2025). "Utilizing combined therapies of antibodies targeting both CD55/CD59 and programmed death 1 (PD-1) results in a collaborative effect that inhibits tumor growth." (PMID 40515636, 2025). "Tumor cells express membrane-bound complement regulatory proteins (mCRP; CD35, CD46, CD55, and CD59) that normal cells use to prevent excessive activation of complement cascades in the early stages of an immune response." (PMID 39125875, 2024). "Tumor cells express membrane-bound complement regulatory proteins (mCRPs; CD35, CD46, CD55, and CD59) that normal cells use to prevent excessive activation of complement cascades in the early stages of an immune response." (PMID 37880350, 2023). "Studies have found that tumor cells can block complement activation cascades and inhibit MAC formation via membrane complement regulatory proteins (mCRPs), such as CD46, CD55, and CD59." (PMID 37907575, 2023). "Of note, seventeen of thirty-nine proteins are reported as urine biomarkers in different diseases, of which eight proteins (PEBP1, EPS8L2, SERPINA1, FGA, SPINT1, CD55, SPARC, and GINM1) are related to neoplastic disease in urine specimens." (PMID 36918772, 2023). "They interacted with the corresponding receptor CD55 and SPN and promoted tumor invasion and metastasis through the adhesion of cancer cells to normal cells." (PMID 37745301, 2023). "Analysis of complement activity within treated tumors revealed that CD55/CD59 double-knockdown resulted in a further increase of C3b deposition, MAC formation, and direct tumor lysis after T+P therapy." (PMID 35167491, 2022). "Taken together, our data indicate that mCRPs, such as CD46, CD55, or CD59, are increased during CTL-mediated immunoediting, and they, especially CD59, contribute to CDC resistance of immune-edited tumor cells." (PMID 35606403, 2022). "Overexpression of membrane bound complement regulators such as CD46, CD55, and CD 59 and blocking complement activation at the level of C3b also prevent CDC and efficient tumor cell killing." (PMID 35860237, 2022). "Analyzes of the relationship between HHE genes and the tumor site in the colon region indicated that four genes, including DUSP4, ZIC2, CD55, and CLDN2 significantly increased in the cecum region (FDR < 0.01)." (PMID 36064367, 2022). "Of the overlapping set of proteins, the levels of WFDC2, S100P, CD55, MDK, THBS2, and MFAP2 were more than 2-fold higher in PDAC compared with tumor-adjacent tissue in our data." (PMID 36923555, 2022). "In this respect, we observed increased expression levels of mCRPs, such as CD46, CD55, and CD59, in P3 tumor cells over the course of CTL-mediated immune editing." (PMID 35606403, 2022). "A major concern is the presence on tumor cells of inhibitory membrane-bound complement regulatory proteins (mCRPs) such as CD46, CD55, and CD59, which enable cancer cells to evade complement attack." (PMID 35052426, 2021). "For example, siRNA-mediated downregulation of CD46, CD55 and/or CD59 on several primary tumors and tumor cell lines sensitizes them to CDC." (PMID 33147799, 2020). "Western blot analysis was used to verify the presence of CD55 across representative samples from adjacent-normal, primary PDAC, PDX F1, and PDX F2 tumours." (PMID 30404163, 2018). "This has shown to be due to the influence of membrane-bound complement regulatory proteins such as CD46, CD55, and CD59 which are overexpressed in tumour cells." (PMID 31544882, 2018). "All cultures were characterized for tumor surface or stem-like marker expression, namely CD46, CD47, CD55, CD56, CD63, CD90, and CD99." (PMID 28545562, 2017).
tumor (continued). "Further, we tested the expression of CD97-related factors (membrane receptors): CD55 (a CD97 ligand), CD44v6 (a cancer stem cell marker), and two potential tumor therapeutic markers, EGFR and HER2." (PMID 26233326, 2016). "In our study we revealed that CD55 is a novel target of HIF-2α in NB cells and that CD55 expression downstream of HIF-2α expression is necessary for tumor cell growth and invasion." (PMID 27043658, 2016). "NPA cells expressed all the three proteins, with a greater expression of CD59 and CD55 than CD46 proteins, suggesting that NPA tumour cells were obviously protected against CDC." (PMID 20145622, 2010). "In NT2-N neuronal cell lines, relatively high expression levels of CD46, CD59 and CD55 are found, however, NT2-N are differentiated from NTERA-2 tumour cells (malignant pluripotent embryonal carcinoma) and tumours are known to overexpress these CReg proteins." (PMID 19721814, 2009). "The lack of MAC was probably due to the expression of C membrane regulators CD46, CD55 and CD59 on the tumour cells." (PMID 15726105, 2005). "Noteworthy membrane-bound CRPs in tumors include CD46, CD55, and CD59, while soluble ones encompass factor I, factor H, and properdin.Although CD46, CD55, and CD59 are pivotal complement regulators expressed across most cell types and tumor cells, they exhibit a double-edged sword role." (PMID 40370471, 2025). "Upregulated by epidermal growth factor receptor (EGFR)/the wingless-related integration site (Wnt) signaling, LINC00973 functions as a ceRNA to sequester miR-216b and miR-150, leading to elevated expression of complement inhibitors CD55 and CD59 on tumor cells." (PMID 41409273, 2025). "Moreover, the combination of anti-CD55/CD59 and anti-PD-1 antibody treatments resulted in a synergistic tumor-suppressive effect." (PMID 40728857, 2025). "On the other hand, the part of CDC in killing tumor cells in vivo is less clear, particularly for solid tumors, in part because tumor cells themselves express membrane-bound complement regulators (CD46, CD55, and CD59)." (PMID 38085594, 2024). "The expression of inhibitory mCRPs like CD46, CD55 and CD59 can protect tumor cells from CDC." (PMID 36119088, 2022). "Both CD55 (decay-accelerating factor [DAF]) and CD59 (protectin) are GPI-anchored CRPs often found upregulated in cancer cells, and they can be expressed either on cell surface or secreted in a soluble form in the tumor microenvironment." (PMID 35167491, 2022). "This phenomenon could be due to the expression of several different complement-regulatory proteins (CRPs) by tumor cells, such as CD46, CD55, and CD59, which inhibit complement activation and confer resistance of tumor cells to killing mediated by CDC." (PMID 35804808, 2022). "Cell adhesion molecules such as ITGA3, CD47, MDK, ITGB1, CD55, and CDH1 show a trend of upregulation with pseudotime, indicating that cell-cell communications play an important role during the evolutionary process of tumor growth and progression." (PMID 35087839, 2021). "We identified four macrophage (Mφ) subpopulations, of which C1QC+ Mφ and CD55+ Mφ (clusters 0 and 4) showed preferential enrichment in adjacent rather than in tumor tissues." (PMID 34185431, 2021). "In addition, CD55 expressed in tumor inhibited the induction of complement-dependent ICOSL+ B cell and dampened anti-tumor immunity, thus become another potential target to enhance anti-tumor immune response." (PMID 33906694, 2021). "Similarly, the membrane-bound complement inhibitors (e.g. CD46, CD55, and CD59) are up-regulated in various primary tumors and tumor lines to evade the complement attack." (PMID 33193442, 2020). "Similarly to these soluble regulators, the membrane-bound C inhibitors CD46, CD55 and CD59 are up-regulated in various primary tumors and tumor lines to evade the C attack." (PMID 33643290, 2020). "Nevertheless, these tumours showed induction of CK8, CK18, GRP78, CD55, CD59 and CD63 mRNAs." (PMID 30820548, 2019).